C1QBP (complement C1q binding protein)
Diseases named in the same sentence as C1QBP in open-access papers (continued):
Sharing a sentence is not in itself a finding about the gene and the disease.
infection (26 papers, 2012 to 2025). The state of being infected such as from the introduction of a foreign agent such as serum, vaccine, antigenic substance or organism. "C1QBP expression of Larimichthys crocea was increased upon infection with Pseudomonas polyglossia, which caused the immune response to visceral leukoplakia." (PMID 40454173, 2025). "We demonstrate for the first time the phenomenon of MBL-dependent enhancement of infections caused by glycosylated virions in low complement conditions and discover roles for C1QBP and dectin-2 in EBOV pathogenesis." (PMID 23573288, 2013). "C1QBP (complement C1q binding protein) is believed to be a multifunctional and multicompartmental protein involved in inflammation and infection processes, and its signaling has been implicated in inhibition of the innate immune response via the PI3K-AKT/PKB pathway." (PMID 32867375, 2020). "C1QBP (complement C1q binding protein) is a protein that is involved in many biological processes, including inflammation, infection, and mitochondrial function and known to interact with FMRP." (PMID 40480633, 2025). "Immunologically, C1QBP is known to be involved in inflammation, autoimmunity, pathogen infection, wound coagulation, and healing." (PMID 36231090, 2022). "A common motif comprised of the genes IKBKE, C1QBP, and EHHADH was found to be directly connected to the HNF4A hub in the infection tolerant state associated with A. baumanii and K. pneumoniae infection." (PMID 35706367, 2022). "Some reports have found that C1QBP is exclusively localised to the mitochondrial matrix, while others find an additional cytoplasmic pool of C1QBP protein which can be recruited to the outer membrane of the mitochondria upon infection with an RNA virus." (PMID 36476844, 2022). "C1QBP knockdown and overexpression cells were established via lentiviral infection and subjected to apoptosis and ROS assay in vitro." (PMID 35693733, 2022). "ROP1 from both RH and PRU parasites co-immunoprecipitates reliably with a host protein, C1QBP, from infections in both mouse and human cells." (PMID 36476844, 2022). "The ILC2s of Cluster 14 expressed Cor1a, Samhd1, Ccl1 (monocyte chemotaxis), Arg1 (promotes acute type 2 inflammation), and C1qbp (involved in multiple infection and inflammatory responses)." (PMID 32351546, 2020). "C1QBP mediates many biological responses in the immune system, including inflammation, infection, and immune regulation." (PMID 32867375, 2020). "In our study, several proteins involved in inflammation and infection processes, such as Annexin A1, Complement component 1 Q subcomponent-binding protein (C1qBP), Poly(rC)-binding protein 2 (hnRNP E2) are indentified." (PMID 24454774, 2014). "The primary role of p32/C1QBP/gC1qR as a receptor to complement protein C1q could be of importance for controlling MDV during the early steps of infection in vivo." (PMID 40828852, 2025). "Therefore, we speculate that C1QBP may play an important role in the cell apoptosis induced by ORFV infection and will conduct experiment to verify this in the further." (PMID 40454173, 2025). "“Bystander” cluster F3 fibroblasts also exhibited increased expression of pro-inflammatory genes, including C1QBP and ISG15, suggesting that cocultured fibroblasts may respond to infection-associated induction of pro-inflammatory signaling by host endocervical epithelial cells." (PMID 37874141, 2023). "C1QBP (Complement Component 1 Q Subcomponent-Binding Protein), a multicompartmental protein, participates in various cellular processes, including mRNA splicing, ribosome biogenesis, protein synthesis in mitochondria, apoptosis, transcriptional regulation, and infection processes of viruses." (PMID 30991713, 2019). "Notably, knock down of C1QBP by both shRNAs was augmented in the presence of MBL but to a significantly greater extent for the most effective shRNA (65% to 90% reduction of infection, p<0.005) suggesting that MBL plays a supplementary role in mediating viral entry." (PMID 23573288, 2013).
infection (continued). "In addition, the expression of c1r, c6, c1qbp and c1qtnf6 in MOS200 or MOS400 groups were higher than that of the control group before or post-infection, which revealed the activation of these genes by dietary MOS and might enhance the anti-infection immunity of M. amblycephala intestines." (PMID 36768530, 2023).
adenocarcinoma (4 papers, 2015 to 2024). A common cancer characterized by the presence of malignant glandular cells. "The protein p32 (also known as gC1qR, C1QBP, or HABP1) is a multicompartmental and multifunctional molecular marker found to be overexpressed in several adenocarcinomas, including colorectal cancer." (PMID 38473963, 2024). "In this regard, the main factor that justifies the application of p32/C1QBP as a therapeutic target is that the protein is significantly overexpressed in many types of adenocarcinomas compared with their non-malignant counterparts." (PMID 38473963, 2024).
myopathy (3 papers, 2017 to 2022). A disease of the muscle in which the muscle fibers do not function properly. "Above all, biallelic mutations in C1QBP are associated with a spectrum of mitochondrial disorders, including myopathy and PEO." (PMID 35326425, 2022). "Biallelic mutations of C1QBP are associated with a spectrum of mitochondrial disorders, including PEO/myopathy; nevertheless, the gene was fully covered in the analysis, without any evidence of a second variant." (PMID 35326425, 2022).
mitochondrial disease (2 papers, 2017 to 2022). "The identification of rare, biallelic C1QBP variants in four individuals with clinically and biochemically confirmed mitochondrial disease adds further evidence for their functional relevance." (PMID 28942965, 2017). "The identification of four different alleles in four affected individuals with a similar clinical and biochemical phenotype from four families establishes C1QBP variants as confidently implicated in recessively inherited mitochondrial disease." (PMID 28942965, 2017). "Disease-associated mutations of C1QBP in mitochondrial disease." (PMID 35310974, 2022).
C1QBP also shares sentences with these, for which no sentence is quoted: malaria (10 papers); Alzheimer disease (3); colorectal carcinoma (3); malignant pleural mesothelioma (3); ovarian carcinoma (3); renal carcinoma (3); cerebral malaria (2); gastric cancer (2); HIV-1 infection (2); osteosarcoma (2); angioedema (1); bacterial pneumonia (1); Barth syndrome (1); brain diseases (1); breast (1); breast invasive ductal carcinoma (1); breast invasive lobular carcinoma (1); cerebral edema (1); chronic pancreatitis (1); cleft palate (1); colitis (1); COVID-19 (1); dementia (1); External ophthalmoplegia (1); hereditary angioedema (1); Hypercholesterolemia (1); in liposarcoma (1); infectious disease (1); infective endocarditis (1); ischaemic stroke (1).
A further 19 diseases each share a sentence with C1QBP in 1 paper.